CDH17 (cadherin 17)
Description:
Cadherins are calcium-dependent cell adhesion proteins. They preferentially interact with themselves in a homophilic manner in connecting cells; cadherins may thus contribute to the sorting of heterogeneous cell types. LI-cadherin may have a role in the morphological organization of liver and intestine. Involved in intestinal peptide transport.
Synonyms: HPT-1; cadherin; CDH16; HPT1
Tractability: Antibody: UniProt places it where antibodies can reach, with high confidence; its Gene Ontology location is reachable by antibodies, with high confidence; UniProt predicts a signal peptide or a membrane-spanning region. PROTAC: ubiquitination databases record sites on it.
Gene: Protein-coding gene on chromosome 8 (94,124,381 to 94,217,303, reverse strand). Ensembl gene ENSG00000079112.
Subcellular location: Cell membrane
Subcellular location (Human Protein Atlas): Cell Junctions; Nucleoplasm
Pathways (Reactome):
Cell-Cell communication: Adherens junctions interactions
Gene Ontology:
Molecular function: integrin binding; protein binding; beta-catenin binding; cadherin binding; proton-dependent oligopeptide secondary active transmembrane transporter activity; calcium ion binding
Biological process: integrin-mediated signaling pathway; positive regulation of integrin activation by cell surface receptor linked signal transduction; adherens junction organization; calcium-dependent cell-cell adhesion; cell adhesion; cell migration; cell morphogenesis; cell-cell adhesion mediated by cadherin; cell-cell junction assembly; homophilic cell-cell adhesion; B cell differentiation; cell-cell adhesion; germinal center B cell differentiation; marginal zone B cell differentiation; spleen development; transmembrane transport
Cellular component: basolateral plasma membrane; cell junction; adherens junction; catenin complex; plasma membrane; cell surface; membrane
Genetic constraint (gnomAD): Loss-of-function variants: 50 observed, 65.94 expected, observed/expected ratio (o/e) 0.76, 90% interval 0.6 to 0.96. The upper end of that interval is the gene's LOEUF score, 0.96, which puts it in group 4 of 6, group 1 being the genes least tolerant of losing a copy. Missense variants: 848 observed, 893.78 expected, observed/expected ratio (o/e) 0.95, 90% interval 0.9 to 1. Synonymous variants: 310 observed, 325.18 expected, observed/expected ratio (o/e) 0.95, 90% interval 0.87 to 1.05.
Homologues: Orthologues: chimpanzee CDH17 (98% identical), macaque CDH17 (95% identical), pig CDH17 (81% identical), rabbit CDH17 (80% identical), mouse Cdh17 (79% identical), dog CDH17 (78% identical), rat Cdh17 (78% identical), guinea pig CDH17 (78% identical), tropical clawed frog cdh17 (48% identical), zebrafish cdh17 (37% identical). Paralogues in human: DCHS2 (24% identical), CDH2 (24% identical), CDH1 (23% identical), CDH23 (23% identical), DCHS1 (23% identical), CDH4 (23% identical), CDH6 (22% identical), CDH18 (22% identical), CDH11 (22% identical), CDH10 (21% identical), CDH12 (21% identical), CDH13 (21% identical), and 21 more.
Diseases named in the same sentence as CDH17 in open-access papers:
CDH17 is named in the same sentence as 84 diseases in open-access papers, as found by Europe PMC text mining. Sharing a sentence is not in itself a finding about the gene and the disease. The quoted sentences say what the papers report.
gastric cancer (37 papers, 2010 to 2026). A primary or metastatic malignant neoplasm involving the stomach. "Functionally, CDH17 has been extensively studied in human gastric cancer, where it is overexpressed and associated with poor prognosis and tumor progression." (PMID 41595482, 2026). "Liver-intestine cadherin (cadherin 17, CDH17) can regulate tumor cell apoptosis signaling pathway, which is associated with the proliferation and adhesion of malignant tumors including gastric cancer, pancreatic cancer and so on." (PMID 35903696, 2022). "In liver and gastric cancers, it is believed that the high expression of CDH17 was associated with poor survival, tumor recurrence, tumor invasion, metastasis and advanced tumor stage." (PMID 24465527, 2014). "Taking all this evidences together, CDH17 can be a diagnostic marker for early stage gastric cancer in Chinese populations." (PMID 24465527, 2014). "The expression level of CDH17 was characteristic of the advanced gastric carcinoma that was associated with poor prognosis; and it was also significantly associated with the lymph node metastasis in gastric cancer." (PMID 24465527, 2014). "Association Between Clinicopathologic Features and CDH17 expression in 156 patients with gastric cancer." (PMID 23554857, 2013). "We then assessed the tumorigenic and metastatic properties (proliferation, colony formation, adhesion, invasion and cell cycle) of the CDH17 deficient gastric cancer cells (shCDH17 cells) compared with the mock vector-infected control cells." (PMID 23554857, 2013). "Notably, increased expression of CDH17 is associated with more aggressive tumor phenotypes and poor survival outcomes in cholangiocarcinoma and gastric cancers." (PMID 39617741, 2024). "Therefore, CDH17 is a promising diagnostic marker, and radiolabeled D2101 has the potential to provide useful information for the N-staging of gastric cancer." (PMID 31605356, 2020). "CDH17 expression was positively associated with a good prognosis of gastric cancer." (PMID 28512631, 2017). "CDH17 may be an effective diagnostic marker for the staging of gastric cancer." (PMID 31605356, 2020). "Overexpression of CDH17 is commonly found in gastric cancer (GC), hepatocellular carcinoma (HCC), and neuroendocrine tumours (NECs), and it has also been reported to distinguish primary adenocarcinoma of the bladder from urothelial carcinoma." (PMID 41155133, 2025). "CDH17 has been shown to regulate integrin signaling and induce downstream Ras activation, which promoted cell proliferation in gastric cancer and CRC." (PMID 39617741, 2024). "In an in vivo study, knockdown of CDH17 in gastric cancer cells suppressed tumor growth and lymphatic metastasis." (PMID 39617741, 2024). "Previous studies have shown that CDH17 is associated with tumor progression and aggressiveness in various types of GI cancers, including CRC, hepatocellular carcinoma, gastric cancer, and cholangiocarcinoma." (PMID 39617741, 2024). "A study published in 2018 targeted the gastric adenocarcinoma cell line AGS with anti-CDH17, an antibody against the extracellular domain of Cadherin-17 (CDH17), which is expressed in gastric cancer." (PMID 36977072, 2023). "CDH17 nanobody-based immunotoxin is potentially a promising therapeutic modality for clinical translation against gastric cancer." (PMID 36435809, 2022). "CDH17 nanobody immunotoxin is a novel and promising modality for targeted therapy in gastric cancer." (PMID 36435809, 2022). "A CDH17 Nanobody fused with toxin PE38 was evaluated for gastric cancer inhibition in vitro and in vivo." (PMID 36435809, 2022). "HOXA13-targeted regulation of CDH17 can affect the Wnt/β-catenin signaling pathway, thus, affecting the progression of gastric cancer." (PMID 35903696, 2022). "Consistent with published studies, TMA data in the present study showed that 66% of gastric cancer samples express CDH17." (PMID 36435809, 2022).
gastric cancer (continued). "In the present study, we identified two CDH17 nanobodies and used them to develop imaging and therapeutic strategies for gastric cancer expressing CDH17." (PMID 36435809, 2022). "In the present study, we identified two nanobodies specifically bound to CDH17 and E8 nanobody was extensively explored for gastric cancer imaging and targeted therapy due to its relatively higher affinity (~ 70 nM)." (PMID 36435809, 2022). "Our findings confirm the potential of CDH17 as a target for gastric cancer or other cancers overexpressing CDH17 by using nanobodies and encourage clinical translation of CDH17 nanobody-based targeted imaging and therapy." (PMID 36435809, 2022). "Collectively, targeting CDH17 with nanobodies represents a new strategy for gastric cancer imaging and therapy." (PMID 36435809, 2022). "Our data demonstrate that CDH17 is a targetable protein for gastric cancer concerning imaging or therapy; and nanobody is a good strategy to design modalities against CDH17 protein." (PMID 36435809, 2022). "CDH17-targeted NIR-PIT suppressed tumor progression in a xenograft model using a CDH-17-expressing gastric cancer." (PMID 35453596, 2022). "To confirm that CDH17 is a better targeting molecule in gastric cancer, we first compared the mRNA expression of three markers (CDH17, HER2 and VEGFR2) in gastric cancer using Genotype Tissue Expression (GTEx) and the Cancer Genome Atlas (TCGA) databases." (PMID 36435809, 2022). "CDH17-positive gastric cancers account for approximately 66% in our tested cohort, which is consistent with previous reports." (PMID 36435809, 2022). "It was reported that approximate 70% gastric cancer and nearly all colorectal cancer express CDH17 with different levels." (PMID 36435809, 2022). "It is reported that CDH17 knockdown inhibits the growth of gastric cancer cells by downregulating Wnt/β-Catenin signaling." (PMID 31605356, 2020). "In the animal study of intratumoral injection of CDH17 shRNA for gastric cancer xenograft mice, the growth of tumors injected with CDH17 shRNA was suppressed compared with control." (PMID 31605356, 2020). "The present study demonstrated that our anti-CDH17 Mab D2101 radiolabeled with 111In has the potential to be an imaging probe for gastric cancer using the CDH17-expressing tumor model AGS cells." (PMID 31605356, 2020). "The positive ratio of CDH17 is approximately 60% in both primary and metastatic gastric cancer, suggesting that CDH17 is a promising marker of gastric cancer." (PMID 31605356, 2020). "On the other hand, the present study revealed higher positive ratios of CDH17 (85.7% [grade 2] and 51.9% [grade 3]) in gastric cancer." (PMID 31605356, 2020). "The immunostaining analysis demonstrated that the CDH17-positive ratio was higher than the HER2-positive ratio in gastric cancer specimens of both primary lesions and LN metastases." (PMID 31605356, 2020). "And then, CDH17 expression in primary and metastatic gastric cancer specimens was evaluated by immunohistochemical analysis to clarify the potential of CDH17 as an N-stage marker." (PMID 31605356, 2020). "Our 111In-anti-CDH17 Mab D2101 depicted CDH17-positive gastric cancer xenografts in vivo and has the potential to be an imaging probe for the diagnosis of primary lesions and lymph-node metastasis in gastric cancer." (PMID 31605356, 2020). "In a healthy adult, the gene that codes for the CDH17 protein is silenced; however, it is often expressed in gastric cancer, as well as other adenocarcinomas." (PMID 33050602, 2020). "CDH17 is highly expressed in gastric cancer, pancreatic cancer, particularly in the exocrine-like subtype of pancreatic ductal adenocarcinoma, Barrett ́s esophagus and associated carcinoma, neuroendocrine tumors, colorectal cancer and hepatocellular carcinoma." (PMID 31324051, 2019). "CDH17 is a known gastric cancer marker while upregulation of CDH1 inhibits pancreatic cancer metastasis." (PMID 29515771, 2018).
gastric cancer (continued). "The characteristics of CDH17 in gastric cancer concerning prognosis or biological significance have been reported, although the correlation between CDH17 expression and prognosis has been controversial." (PMID 27580354, 2016). "Tissue microarrays constructed using primary lesions and nodal metastases of 106 advanced gastric cancers revealed CDH17 and CLDN18 expression in 98 positive cases of 106 (92%)." (PMID 27580354, 2016). "In summary, we identified a useful pair of target molecules, CDH17 and CLDN18, to aid in the comprehensive detection and localization of gastric cancer metastases in vivo to overcome challenges associated with intratumoral heterogeneity." (PMID 27580354, 2016). "CDH17 is overexpressed in hepatocellular carcinoma, gastric cancer, ductal pancreatic cancer and colorectal cancer." (PMID 24465527, 2014). "Cadherin-17 (CDH17), one member of 7D-cadherin superfamily, was overexpressed in gastric cancer (GC) and was associated with poor survival, tumor recurrence, metastasis, and advanced tumor stage." (PMID 24465527, 2014). "In current study, a co-immunoprecipitation of CDH17 with integrin β1, integrin β4, integrin β5, and integrin α2 was conducted in gastric cancer AGS cells, respectively." (PMID 24465527, 2014). "Tissue microarray analysis of CDH17 and clinical pathological characteristics in Chinese gastric cancers." (PMID 24465527, 2014). "Taking all this evidences together, we can conclude that there is a significant correlation between CDH17 expression and the tumorigenic and metastatic abilities of gastric carcinoma, and CDH17 can serve as a potential therapeutic target for future research." (PMID 24465527, 2014). "In the present study, we demonstrate that CDH17 is an oncogene and an attractive therapeutic target in gastric cancer: CDH17 is highly expressed in tumor tissues, with almost half of gastric cancers being CDH17 positive by IHC." (PMID 23554857, 2013). "We interrogated several pathways in order to discover the molecular mechanism of CDH17 knockdown-mediated inhibition of gastric cancer growth, proliferation and metastasis." (PMID 23554857, 2013). "Together, these observations point to a potential oncogenic role for CDH17 in gastric cancer though Wnt/β-catenin pathway." (PMID 23554857, 2013). "We believe that CDH17 inhibition is an attractive therapeutic target in gastric cancer that should be explored in the near future." (PMID 23554857, 2013). "In conclusion, our study provides direct evidence of CDH17 as a bona fide oncogene in gastric cancer." (PMID 23554857, 2013). "According to our results, CDH17 is an oncogene and an attractive therapeutic target in gastric cancer." (PMID 23554857, 2013). "Mouse models of gastric cancer were used to validate the effect of targeting CDH17 as a potential treatment." (PMID 23554857, 2013). "In contrast, CDH17 was highly expressed in gastric cancer in almost 50% of patients.Currently, standard therapy for gastric cancer includes surgery with optimal debulking of disease followed by cytotoxic therapy." (PMID 23554857, 2013). "It was also unexpected that CDH-17 (LI-cadherin), thought to be an intestinal marker gene, expresses in almost all the gastric cancer cell lines including sig-type." (PMID 23451082, 2013). "We demonstrated the dramatic effect of CDH17 suppression in gastric cancer cells and proposed a mechanism of malignant transformation through the Wnt/β-catenin signaling pathway." (PMID 23554857, 2013). "Here, we aimed to dissect the oncogenic signaling mechanisms of CDH17 in the gastric carcinoma context and evaluated the effects of targeting CDH17 as a potential therapeutic approach for gastric cancer." (PMID 23554857, 2013). "Taken together, these results suggest that CDH17 is important for initiation and metastasis of gastric cancer; at least a subset of well-credentialed gastric carcinoma cell lines retains expression of CDH17 allowing for further functional characterization." (PMID 23554857, 2013).
gastric cancer (continued). "CDH17 was consistently up-regulated in human gastric cancers, and overall survival in patients with CDH17 upregulation was poorer than in those without expression of this gene (5 yrs overall survival rate 29.0% vs. 45.0%, P<0.01)." (PMID 23554857, 2013). "The antitumor effect of CDH17 knockdown was also seen in the metastatic gastric carcinoma cell line MKN-45." (PMID 23554857, 2013). "Collectively, CDH17 expression is a useful prognostic marker in gastric carcinoma and appears to be related to tumor progression." (PMID 23554857, 2013). "Previous studies of clinical cohorts identified CDH17 as a potential disease marker for gastric carcinoma." (PMID 23554857, 2013). "First of all, we examined the expression level of CDH17 in 156 gastric carcinoma specimens by IHC: 69 (44.3%) of 156 cases were positive, whereas the remaining 87 cases (55.7%) were negative or weak for CDH17 expression." (PMID 23554857, 2013). "Following previous studies that identified the adhesion molecule Cadherin-17(CDH17) as a potential marker for gastric carcinoma, we performed proof-of-principle studies to develop rational therapeutic approaches targeting CDH17 for treating this disease." (PMID 23554857, 2013). "CDH17 shRNA-mediated knockdown resulted in significantly reduced cell growth of gastric carcinoma cell lines (P<0.001) (Right)." (PMID 23554857, 2013). "The effect of RNA interference–mediated knockdown of CDH17 on proliferation of gastric carcinoma cell lines was examined in vitro and in vivo, as well as the effects on downstream signaling by immunoblotting." (PMID 23554857, 2013). "Next, we knocked down CDH17 in gastric carcinoma cell lines—AGS and MKN-45 using CDH17-specific shRNAs." (PMID 23554857, 2013). "Immunohistochemistry was used to study the expression of CDH17 in 156 gastric carcinomas, and the relationship between survival and CDH17 expression was studied by multivariate analyses." (PMID 23554857, 2013). "Our results identify CDH17 as a biomarker of gastric carcinoma and attractive therapeutic target for this aggressive malignancy." (PMID 23554857, 2013). "Recent studies comparing gastric cancer and normal tissue have identified a number of genetic markers, including diagnostic markers [NF2, INHBA, SFRP4], prognostic markers [CD9, CDH17, PDCD6], and gastric cancer-associated genes [MUC13, CLDN1, Ki67 and CD34]." (PMID 22133303, 2011). "This insight has led researchers to explore CAR-T cells that target CDH17 for the treatment of colorectal, small cell lung, and gastric cancer, suggesting that CDH17 may similarly mediate stemness and chemoresistance in CTC-TJH-01 cell clusters." (PMID 39994505, 2025). "We demonstrated that CR@E8-EVs could specifically target the CDH17-positive gastric cancer cells, and accomplish the PA imaging-guided PTT in a gastric tumor model leveraging excellent photothermal conversion capability of CR-DPA-T." (PMID 37993888, 2023). "Here, we firstly reported that CDH17 nanobody E8 engineered EVs secreted from normal human embryonic kidney (HEK-293) cultures were loaded with a NIR SOPTA (CR-DPA-T) for PA imaging-guided PTT in a gastric cancer model." (PMID 37993888, 2023). "Collectively, the present results disclose that E8 nanobody could target CDH17-overexpressing tumor tissues with excellent specificity and precision, and is a promising candidate agent for gastric cancer targeted imaging." (PMID 36435809, 2022). "This nanobody-based immunotoxin was extensively tested its activity in vitro and in vivo, showing superb anti-proliferation effect on CDH17-overexpressing gastric cancer cell lines, and significantly inhibits the tumor growth and prolongs the survival in CDH17-positive CDX and PDX models." (PMID 36435809, 2022). "The E8 nanobody as a lead could be used for the rapid imaging detection of CDH17-positive gastric cancer and highly efficiently deliver toxin PE38 into tumor tissues." (PMID 36435809, 2022).